CT47A3 (cancer/testis antigen family 47 member A3)
Synonyms: CT47.3
Gene: Protein-coding gene on chromosome X (120,972,746 to 120,976,068, reverse strand). Ensembl gene ENSG00000236126.
Subcellular location (Human Protein Atlas): Nucleoli
Homologues: Orthologues: macaque CT47B1 (77% identical). Paralogues in human: CT47A1 (100% identical), CT47A10 (100% identical), CT47A11 (100% identical), CT47A12 (100% identical), CT47A2 (100% identical), CT47A4 (100% identical), CT47A5 (100% identical), CT47A6 (100% identical), CT47A7 (100% identical), CT47A8 (100% identical), CT47A9 (100% identical), CT47B1 (86% identical), and 1 more.